DGCR6L (DiGeorge syndrome critical region gene 6 like)
Description:
May play a role in neural crest cell migration into the third and fourth pharyngeal pouches.
Synonyms: FLJ10666; DGCR6
Tractability: PROTAC: ubiquitination databases record sites on it.
Gene: Protein-coding gene on chromosome 22 (20,314,238 to 20,320,080, reverse strand). Ensembl gene ENSG00000128185.
Subcellular location: Nucleus
Gene Ontology:
Molecular function: protein binding
Cellular component: nucleus
Genetic constraint (gnomAD): Loss-of-function variants: 24 observed, 30.17 expected, observed/expected ratio (o/e) 0.8, 90% interval 0.57 to 1.12. The upper end of that interval is the gene's LOEUF score, 1.12, which puts it in group 4 of 6, group 1 being the genes least tolerant of losing a copy. Missense variants: 218 observed, 285.05 expected, observed/expected ratio (o/e) 0.76, 90% interval 0.68 to 0.86. Synonymous variants: 104 observed, 123.45 expected, observed/expected ratio (o/e) 0.84, 90% interval 0.72 to 0.99.
Homologues: Orthologues: chimpanzee DGCR6L (99% identical), macaque DGCR6 (96% identical), macaque DGCR6L (96% identical), dog DGCR6L (85% identical), guinea pig Dgcr6l (84% identical), mouse Dgcr6 (82% identical), rat Dgcr6 (81% identical), tropical clawed frog dgcr6 (61% identical), zebrafish dgcr6 (57% identical), Drosophila melanogaster gdl (33% identical). Paralogues in human: DGCR6 (97% identical).
Diseases named in the same sentence as DGCR6L in open-access papers:
DGCR6L is named in the same sentence as 2 diseases in open-access papers, as found by Europe PMC text mining. Sharing a sentence is not in itself a finding about the gene and the disease. The quoted sentences say what the papers report.
chromosome 22q11.2 deletion syndrome (2 papers, 2017 to 2022). "In 2012, researchers reported on dysregulation of DGCR6 and DGCR6L and the psychopathological outcomes in chromosome 22q11.2 deletion syndrome." (PMID 35547101, 2022).
anxiety disorder (1 paper, 2022). A category of psychiatric disorders which are characterized by anxious feelings or fear often accompanied by physical symptoms associated with anxiety. "Their investigation revealed that low expression levels of the vital genes DGCR6 and DGCR6L are associated with the observed variability in anxiety disorders in children with 22q11 deletion syndrome." (PMID 35547101, 2022).